LINC01247 (long independently transcribed non-coding RNA 1247)
Gene: Long non-coding RNA gene on chromosome 2 (6,366,010 to 6,375,422, reverse strand). Ensembl gene ENSG00000227007.
Diseases named in the same sentence as LINC01247 in open-access papers:
LINC01247 is named in the same sentence as 1 disease in open-access papers, as found by Europe PMC text mining. Sharing a sentence is not in itself a finding about the gene and the disease.
LINC01247 shares sentences with these, for which no sentence is quoted: COVID-19 (1 paper).